MCL1 (MCL1 apoptosis regulator, BCL2 family member)
Diseases named in the same sentence as MCL1 in open-access papers (continued):
Sharing a sentence is not in itself a finding about the gene and the disease.
tumor (continued). "These factors also increase the survival of tumor cells via upregulation of anti-apoptotic proteins like B-cell lymphoma-2 (BCL-2) and myeloid cell leukemia-1 (MCL-1) or downregulation of pro-apoptotic proteins like BCL-2 Associated X protein (BAX)." (PMID 33114328, 2020). "Although MCL-1 plays a role in normal physiological processes, including cardiac and hepatic tissues, overexpression of MCL-1 and increased oncogenic addiction of tumor cells has emerged as a common determinant of venetoclax resistance." (PMID 33139702, 2020). "In agreement with in vitro studies, in tumours treated with alvocidib we observed downregulation of the marker of proliferation Ki67 as well of MYC, Survivin and MCL‐1, and upregulation of BIM and p21(and EV5B and C)." (PMID 32558295, 2020). "It promotes MCL cells to enter the peripheral circulation by inhibiting chemokine and BCR signals and downregulating the expression of MCL1 in MCL cells, thereby overcoming tumor microenvironment-related drug resistance." (PMID 33292251, 2020). "Previous studies showed that upregulation of the Bcl-2 family member, myeloid cell leukemia sequence 1 (Mcl-1), is involved in EGFR signaling-mediated tumor cell survival." (PMID 32081857, 2020). "Previous studies have shown that JNK inhibitors exerted their therapeutic effect in tumor through regulating the downstream effectors, such as c-MYC and MCL-1." (PMID 32552902, 2020). "While the majority of these genes and pathways are pro-immune and pro-apoptotic it is noted that several, such as MCL1, Bcl6, IL-7R, and SOCS are believed, in some situations to be immune regulatory and/or pro-tumor survival." (PMID 32757666, 2020). "This cellular reprogramming was characterized by an up-regulation of ATM, MLH1, MCL1 and MITF, genes known to be involved in DNA repair, cell survival and proliferation - essential pathways for tumor survival under stressful conditions like chemotherapy." (PMID 31597943, 2019). "The TYK2–pYSTAT1 pathway positively regulates MCL1 expression in ALCL cells, contributing to this aberrant tumor cell survival." (PMID 30131584, 2019). "In vivo, the downregulation of MARCH1 by treatment with SAF markedly inhibited tumor growth, suggesting that SAF partly blocks MARCH1 and further regulates the PI3K/AKT/β-catenin and antiapoptosis Mcl-1/Bcl-2 signaling cascade in the HCC nude mouse model." (PMID 30678274, 2019). "One such approach is the “BH3 profiling” of tumor cells, in which BH3 peptides interacting with Bcl-2, Bcl-xl, or Mcl-1 are used to identify the dependence of tumor cells on the respective anti-apoptotic Bcl-2 proteins." (PMID 31312616, 2019). "In line with our in vitro findings, CDKI‐73 also reduced the level of Mcl‐1 and Bcl‐2, which was accompanied by induction of apoptosis indicated by cleavage of PARP when compared with the vehicle‐treated tumours." (PMID 31398271, 2019). "To examine the response of WB1P and WB1P-Myc tumors to MCL1-inhibition, we transplanted WB1P and WB1P-Myc organoids orthotopically into nude mice (n = 10 per line) and tested the response of the tumor outgrowths to S63845." (PMID 30674894, 2019). "While it cannot be excluded that MYC overexpression reshapes evolution of BRCA1-deficient TNBCs via negative selection of tumor cell clones with high levels of CNAs, amplifications of MCL1 might be particularly selected for as they may counteract the pro-apoptotic effects of MYC overexpression." (PMID 30674894, 2019). "Overall, these data suggest that MAPK inhibition can lead to dependence on MCL-1 in vivo and that therapeutic targeting using BRAF and MCL-1 inhibitors can induce profound tumor (in some cases pathologic complete responses) in tumor-bearing mice." (PMID 31727958, 2019). "In the tumor tissues formed by HepG2 cells transfected with si-C1QTNF1-AS1, the expression of miR-221-3p, SOCS3, p-STAT3, c-Myc and MCL-1 was increased, decreased, increased, increased and increased, respectively." (PMID 31222560, 2019).
tumor (continued). "This screen showed a marked depletion for shRNAs targeting Mcl1, indicating that MCL1 expression is essential for growth of WB1P-Myc tumor cells." (PMID 30674894, 2019). "We found that Myeloid cell leukemia-1 (MCL1), a member of the BCL-2 family of tumor suppressors and a predicted target of miR-101-3p, was downregulated in our microarray data." (PMID 31864341, 2019). "As in various tumor lines, treating NALM-6 for 6 h with 1 or 10 mM 2DG markedly reduced MCL-1 (top)." (PMID 30538285, 2019). "PIK-75, flavopiridol and SNS-032 reduced MCL-1 levels in each genotype in a dose-dependent manner, even in the Mcl-1tg/MLL-AF9 tumours." (PMID 30470795, 2019). "IHC analysis revealed that BETd-260 suppresses Mcl-1 expression, increases Bad expression, and triggers robust apoptosis in HCC xenograft tumor tissues." (PMID 31993368, 2019). "To definitively establish the extent of tumor response, we excised the tumor site from several BRAF/MCL-1 inhibitor-treated mice." (PMID 31727958, 2019). "Survivin, Mcl-1, and VEGF are examples of tumor-related factors whose expressions are thought to be regulated by STAT3." (PMID 30755233, 2019). "qPCR analysis indicated that the expression levels of anti-apoptotic proteins Bcl-x, Mcl-1 and FLIP were significantly higher in PDAC tumor tissues than in the normal pancreas tissues." (PMID 29409480, 2018). "We perform a human deubiquitinase short interfering RNA (siRNA) library screen and identify that USP13 (ubiquitin-specific protease 13) functions as a novel MCL1 DUB to enhance its stability and promote tumor survival." (PMID 29335437, 2018). "Here, the authors show that MCL1’s stability is regulated by deubiquitinase USP13, and its inhibition sensitises tumor cells to BH3 mimetic inhibitors." (PMID 29335437, 2018). "Delivery of Mcl-1 siRNA loaded into polymeric nanoparticles (MCL1 si-NPs) decreased Mcl-1 expression in LTED-selected and fulvestrant-treated cells, increasing tumor cell death and blocking tumor cell growth." (PMID 29343814, 2018). "The literature suggests that in other tumor entities, including GBM, the efficacy of Mcl-1 inhibitors is dramatically increased in the presence of other drug compounds." (PMID 30478285, 2018). "MiR-29a and miR-150 were both shown to be tumor suppressors that, respectively, sensitized NPM-ALK(+) ALCL cells to doxorubicin-induced apoptosis through MCL-1 targeting, and reduced cell growth and viability through MYB." (PMID 29581862, 2018). "Quercetin and green tea reduced tumor growth in HL-60 xenografts accompanied by decreased expression of anti-apoptotic proteins, BCL-2, BCL-XL and MCL-1 and increased expression of BAX, a pro-apoptotic protein." (PMID 29472583, 2018). "This is in line with recent studies with an additional MCL-1-specific BH3 mimetic, S63845, which showed tumour-specific cell killing in xenograft models of haematological cancers." (PMID 29339815, 2018). "A genetic HCC mouse model was employed to assess the ability of metformin to reduce tumor formation, induce apoptosis, and control 4E-BP1 activation and Mcl-1 protein expression." (PMID 28881582, 2017). "HUWE1 is an E3 ubiquitin ligase that controls the stability of MCL1, MYC and MYCN functions which would suggest a tumour‐suppressive role." (PMID 28003334, 2017). "The anti-tumor effect of dinaciclib is likely mediated through cell cycle inhibition and apoptosis induction given that CKD1, cyclin B1, Aurora A, Mcl-1, Bcl-xL, survivin and pro-caspase-3 levels were all decreased." (PMID 28207834, 2017).
tumor (continued). "Numerous studies have reported that Mcl-1 protein levels are inhibited by targeting PI3K/Akt and/or mTOR pathways using specific inhibitors, leading to increased tumor cell killing in both in vitro and in vivo models." (PMID 29228561, 2017). "The synergistic anti-tumor activity of JQ1 and ABT-263 is through up-regulation of Bim, and disturbing the interaction of Bim with Bcl-2 and Mcl-1." (PMID 29156797, 2017). "Next, we measure the levels of STAT3 phosphorylation in tumor samples and found that the in vivo treatment of luteolin significantly downregulated STAT3 phosphorylation and Mcl-1, Bcl-xl, Survivin expression at both protein and transcription levels." (PMID 28182003, 2017). "Through inducing ROS-mediated degradation of Mcl-1 ubiquitination, the triple combination of 5-FU, DTN and DHA resulted in the elevated apoptosis in CRC cells, thus to reduce the tumor size and weight." (PMID 28881661, 2017). "FBXW7 is a tumor suppressor that regulates degradation of oncogene proteins such as MYC, cyclin E, Notch, and MCL1." (PMID 28464881, 2017). "We found that SC‐60 treatment showed reduced tumor weight and suppressed tumor growth, increased SHP‐1 activity, and decreased p‐STAT3 and Mcl‐1 expressions in xenografted tumors." (PMID 28084011, 2017). "Over-expression of [GRP78 and HSP27] prevented: AR-12 –induced activation of ER stress signaling and maintained mTOR activity; AR-12 –mediated down-regulation of thioredoxin, MCL-1 and c-FLIP-s; and preserved tumor cell viability." (PMID 26887051, 2016). "This study and several previous studies show that, in addition to inducing accumulation of tumor-suppressive proteins, MLN4924 also dramatically increases levels of several pro-survival oncogenic proteins, such as cyclin E and Mcl-1." (PMID 27223074, 2016). "The regulation of pro- and anti-apoptotic proteins in imiquimod treated tumour cells has been well established, with several studies measuring changes to BCL2, MCL1, A20 and Noxa after treatment." (PMID 27936237, 2016). "On the basis of the microarray data, we chose to focus on MCL-1 and JAK3 genes which appeared downregulated in tumor-reactive CD8+ T cells from RCC patient." (PMID 27063186, 2016). "Our data suggest that the tumor suppressor miR-101 represses TNBC progression and sensitizes TNBC cells to paclitaxel treatment by directly targeting MCL-1." (PMID 26036638, 2015). "Evaluating with Oncomine data, we found most target genes (BCL2, ERBB2/3, SIRT7, ETS1, Mcl-1, IL6R, and LIN28B) were significantly activated in HCC tumor tissues, consistent with miR-125b underexpression." (PMID 25861255, 2015). "A substituted derivative of S1 was designed and characterized as showing a higher affinity for binding MCL-1 (10 nM) and BCL-2 (20 nM) and a better apoptotic activity in tumor cell lines than the parental S1." (PMID 25970783, 2015). "FBW7 exerts its anti-tumor activity by targeting a ever-growing list of ubiquitin substrates including MED13, KLF2, and Mcl-1." (PMID 24899581, 2014). "However, though Mcl-1 overexpression in GIST was related to poor survival in this study, we have also noted the lack of association of strong Mcl-1 expression with mitotic rate, tumor size, and tumor location, three widely recognized and strongly validated prognostic parameters of GISTs." (PMID 24947165, 2014). "In GIST tumor specimens, increased expression of OPN and Mcl-1 can also be observed by immunohistochemical staining." (PMID 24947165, 2014). "A number of studies have shown that Mcl-1 is a key resistant factor for ABT-737 and ABT-263 in a variety of tumor types." (PMID 24901320, 2014). "To further evaluate the clinicopathologic significance of Mcl-1 expression in GIST, we use the mean tumor Mcl-1 expression value of 0.8 by western blotting as the cut-off level to define Mcl-1 activity in patients with GIST." (PMID 24947165, 2014). "HIF-1α knock-down also sensitized tumor cells to IMQ-induced apoptosis, with the rapid depletion of the Mcl-1 protein." (PMID 24658058, 2014).
tumor (continued). "Among these, we validated EZH2, MCL-1 and FOS as direct targets of miR-101 and silencing of these genes mimics the tumor suppressive effects observed on promoting microRNA-101 function." (PMID 25153722, 2014). "All our findings suggested that WNT5B/MCL1 cascade is critical for TNBC and understanding its regulatory apparatus provided valuable insight into the pathogenesis of the tumor development and the guidance for targeting therapeutics." (PMID 24564888, 2014). "Furthermore IL-6 may also provide tumor cells with mechanisms to escape cell death induced by stress and cytotoxic drugs, such as increased expression of several survival proteins, i.e. Bcl-2, Bcl-xL, Mcl-1, survivin, and XIAP." (PMID 23517603, 2013). "miR-101 has mainly been studied for its tumor suppressive functions, by directly targeting EZH2, Cox-2, Mcl-1 and Fos." (PMID 23414127, 2013). "Enforced miR-29a expression reduced Mcl-1 expression in ALCL cells and reduced tumor growth in a xenografted model." (PMID 23431463, 2013). "Promoting Mcl-1 ubiquitination and degradation using USP9X inhibitor sensitizes tumor cells to various chemotherapies including Bcl-2/Bcl-xL inhibitors." (PMID 23171055, 2012). "Mcl-1, Bcl-xL and USP9X overexpression are tumor survival mechanisms protective against chemotherapy." (PMID 23171055, 2012). "IL-7 protected human T cells after a short co-culture with tumor cells in vitro, and inhibitors of PI3K/AKT pathway and siRNAs against Mcl-1 and Bim were used to evaluate the role of these signaling pathways in IL-7 protection." (PMID 22680924, 2012). "STAT3 activation can upregulate the expression of anti-apoptotic proteins (Bcl-2, Mcl-1 and Bcl-x), proliferation related proteins (cyclin D1 and c-Myc) and angiogenesis promoting factors (VEGF) to prevent tumor cells from apoptosis." (PMID 23554768, 2012). "It has been reported that the activity of GSK-3β was required for Mcl-1 degradation, which is an essential mechanism for GSK-3β-induced apoptosis and contributes to GSK-3β-mediated tumor suppression and chemosensitization." (PMID 22046442, 2011). "The combination of Mcl-1 down-regulation and ABT-737 appears to be an efficient means of inducing apoptosis in multiple tumor types." (PMID 19684859, 2009). "The STAT3 signaling pathway, crucial for tumor growth and survival, was significantly inhibited by faberidilactone A, as evidenced by reduced STAT3 phosphorylation and downregulation of downstream targets such as cyclin D1 and Mcl-1." (PMID 40076318, 2025). "In task 3, ChatGPT was used to design non-covalent inhibitors for MCL1, a BCL2 family protein linked with poor tumor outcomes." (PMID 41454019, 2025). "In addition, MCL1 and BCLXL have been shown to reduce the anti-tumour efficacy of AR targeting therapies and chemotherapies in PCa." (PMID 41438049, 2025). "In addition, accumulated bile salts, such as glycochenodeoxycholic acid (GCDC), promote tumor cell survival and confer resistance to chemotherapy through the extracellular signal-regulated kinase/myeloid cell leukemia-1 (ERK/MCL-1) signaling pathway." (PMID 40980688, 2025). "MCL-1 and BCL-6 gene expression showed significant associations with advanced stage and high tumor grade (P < 0.001), but not with menopausal status or hormone receptor status (P > 0.05)." (PMID 40612845, 2025). "Although deletions of the FAM172a region (5q15) do not occur in human MM, amplifications of MCL1 (1q21) are common and have been reported to be acquired with tumor progression." (PMID 38714690, 2024). "Consistent with the scRNAseq data, metastases in both cell lines had higher MCL1 expression than the primary tumor regardless of the metastatic time point." (PMID 37676378, 2024).
tumor (continued). "This is important because the ideal MCL1 inhibitor would provide sufficient exposure to induce MCL1-dependent tumor cell death but not beyond that so as to minimize on-target toxicity." (PMID 39179926, 2024). "In addition, mice receiving injections of T cells that were pre‐cultured with G‐CSF/GM‐CSF or Mcl‐1 antibody‐treated TCNs exhibited increased CD8+ T cell infiltration and decreased Ki67‐ or PCNA‐positive cells, indicating reduced proliferation of tumor cells." (PMID 39447112, 2024). "Thus, both ER stress signaling and reduced STAT3 signaling play overlapping roles in regulating MCL1 and BCL-XL levels that regulates tumor cell viability after drug exposure." (PMID 38758815, 2024). "Because apoptosis is irreversible, prolonged exposure to MCL1 inhibitors is not required for effective tumor reduction." (PMID 39179926, 2024). "However, tumor growth was significantly reduced by S64315 in the immunocompetent C57BL/6 J mice (p < 0.001), suggesting an immunomodulatory role for this MCL1 inhibitor." (PMID 38459020, 2024). "The findings indicated that TTCS‐conditioned neutrophils significantly inhibited the cytotoxicity of tumor‐specific CD8+ T cells, and this effect could be effectively attenuated by blocking G‐CSF and/or GM‐CSF or using anti‐Mcl‐1 antibody on neutrophils." (PMID 39447112, 2024). "Herein, it is observed that apoptosis of TANs is significantly delayed owing to induction by tumor‐derived G‐CSF and GM‐CSF through the activation of the PI3K‐AKT signaling pathway, upregulation of anti‐apoptotic Mcl‐1 expression, and downregulation of activated Caspase‐3 levels." (PMID 39447112, 2024). "Although we observed intra-tumor heterogeneity, Bcl2l1 expression in tumor lesions was higher than in non-tumor lesions in all states, whereas Mcl1 expression was less tumor-specific and relatively lower in recurrent lesions." (PMID 39122703, 2024). "Given SMARCA2 degradation failed to meet expectations for tumour efficacy, combinations were explored, which led to identification of in vitro sensitisation to apoptosis through combination with MCL1 inhibitors." (PMID 36720862, 2023). "In contrast, other compounds such as doxorubicin and SNS-032 non-specifically downregulated MCL-1 in tumor cells as well as in normal cells." (PMID 36588105, 2023). "In contrast, by combining AZD8055 with platelet-sparing BCL-XL degrader DT2216, we achieved tumor-selective targeting of both MCL-1 and BCL-XL, respectively, without significant on-target toxicity both in cell culture and in mice." (PMID 36588105, 2023). "To evaluate whether AFP immunization can be effective against AFP(+) HCC, we applied the c-MYC/Mcl1–induced mouse HCC model by hydrodynamic tail vein injection (HDTVi), which exhibited high Afp expression in tumor cells." (PMID 37040183, 2023). "Another significant result from our preclinical study is that AFP immunization has no efficacy against already-formed c-MYC/Mcl1 tumor lesions due partly to immune escape from AFP-specific T cells." (PMID 37040183, 2023). "These oncoprotein substrates include cyclin E, c-JUN, c-Myc, NOTCH-1, MCL-1 and KLF5, predominantly comprising transcription factors or key signaling molecules that regulate a wide range of cellular process involved in cell proliferation and tumor progression." (PMID 38027013, 2023). "The first potent and MCL-1 specific inhibitor described in animal studies was S63845 and this was efficacious in rodent models at reducing tumor burden, without adverse events." (PMID 37864894, 2023). "Thus, similar to our approach for limiting M.tb in a granuloma model, other labs have queried if specifically inhibiting MCL-1 and BCL-2 would limit tumor burden of cells that highly express both BCL-2 and MCL-1." (PMID 37864894, 2023). "In addition, the upregulation of the BCL2 homolog MCL1 is more common in TNBC and has been shown to be correlated with an increased tumor size and invasion." (PMID 37760451, 2023).